MCL1 (MCL1 apoptosis regulator, BCL2 family member)
Diseases named in the same sentence as MCL1 in open-access papers (continued):
Sharing a sentence is not in itself a finding about the gene and the disease.
cancer (continued). "Moreover, b‐AP15 induced cleavage of PARP and caspase 3, as well as downregulation of Mcl‐1 and upregulation of Bax, further supporting the anti‐cancer activities of b‐AP15 in CML." (PMID 36082692, 2022). "Inhibiting these Mcl-1 stabilizing mechanisms may enhance the tumor-killing efficacy in Mcl-1-dependent cancer cells." (PMID 36045907, 2022). "The elevation of MCL-1 during tumor development may also impart an intrinsic resistance to cancer therapy." (PMID 35349392, 2022). "The use of Mcl-1 inhibitors in combination with other critical molecular inhibitors has recently been shown to be a potential method for triggering cell death pathways in cancer therapy." (PMID 35745769, 2022). "A number of reports have demonstrated the importance of Mcl-1 for chemoresistance in cancer cells." (PMID 36045907, 2022). "It was found that nordentatin inhibited the proliferation and migration of SH-SY5Y cells by inhibiting GSK-3 phosphorylation, which controls the expression of Mcl-1 (antiapoptotic protein), resulting in the activation of cleaved caspase-3 and the apoptosis of cancer cells." (PMID 35723293, 2022). "For example, a patient presenting a low expression of Mcl-1 in 100% of their cancer cells could be globally more sensitive to ABT-737 than another in whom 30% of cancer cells strongly express Mcl-1." (PMID 36303844, 2022). "Assessing the interaction of BCL-2 family proteins using immunoprecipitation upon exposure of ALL cells to BH3-mimetics, we observed decreased binding of BIM to BCL-2 upon exposure to venetoclax, but compensational increased binding to MCL-1 in other cancer cell types." (PMID 35031695, 2022). "Our data indicate that MCL1 and Bcl-xL cooperate at the mitochondria level to promote cancer cell survival, and MCL1 nuclear localization reconstitutes sensitivity to Bcl-xL inhibitors, phenocopying functional inhibition, or genetic ablation of MCL1 as is illustrated in our proposed model." (PMID 35042842, 2022). "Moreover, miR-29s induced apoptosis in cancer cells by negatively regulating anti-apoptotic proteins such as MCL-1, VDAC1/2, and CDC42/p85 complex." (PMID 36140219, 2022). "FBW7 recognizes c-Myc, Mcl-1, and other oncogenic proteins for ubiquitination and subsequent proteasomal degradation, which is closely related to the proliferation, apoptosis, invasion, and metastasis of cancer cells." (PMID 36457505, 2022). "Interestingly, an expression survey of Bcl-2 family proteins across an array of cancer cell lines of diverse lineages demonstrated a predominant overexpression of Mcl-1, underscoring its role as a key prosurvival protein for tumor cells." (PMID 36045907, 2022). "Distinct BCL-2 family proteins may play differentially prominent roles in individual cancers, and biomarkers to reveal potential sensitivity to MCL-1 inhibition would allow effective tailoring of treatment." (PMID 35349392, 2022). "Downregulation of Mcl-1 promotes apoptosis in various cancer cells." (PMID 36039387, 2022). "MCL1 encodes a BCL-2 family protein that inhibits apoptosis by regulating mitochondrial outer membrane permeabilization, and MCL1 overexpression is generally correlated with poor prognosis and resistance to most cancer therapeutics." (PMID 35338135, 2022). "Bcl-2 and Mcl-1 are overexpressed in some cancer cells, particularly after treatment." (PMID 35745769, 2022). "Indeed, the ratio of caspase-8 to FLIP, or caspase-8 to MCL-1 were more predictive of response to MEDI3039 in several major cancer types compared with single biomarker analyses when using either protein or mRNA expression levels." (PMID 35086954, 2022). "It further increased after radiation and has been reported to increase radiation resistance via regulating B-cell lymphoma-2 (Bcl-2)/Bcl-2-associated X protein (Bax), forkhead box proteins O1 (FoxO1), or myeloid cell leukemia sequence 1 (Mcl-1)/p-CHK1 in different cancer types." (PMID 35875060, 2022).
cancer (continued). "This shared biochemical characteristic, i.e. MCL‐1 by both cancer and Leishmania may provide significant therapeutic advantages if targeted in new drugs design." (PMID 35648075, 2022). "The ability of MCL1 to inhibit apoptosis by binding to the BH3 domains of pro-apoptotic Bcl-2 family members is a well-studied means by which this protein confers resistance to multiple anti-cancer therapies." (PMID 35042842, 2022). "In addition, myeloid cell leukemia-1 (Mcl-1) is an antiapoptotic protein that regulates apoptosis sensitivity in many cancers." (PMID 36505792, 2022). "However, the sensitivity of cancer cells to Hsp90 inhibitors can be restored following inhibition of MCL-1." (PMID 35346215, 2022). "Thus, besides the anti-apoptotic role, MCL-1 plays an important activity in migration, metastasis and development of a variety of cancer cells." (PMID 36158686, 2022). "The ABT-199 induced transactivation of NOXA described here might re-sensitize resistant cancer cells or MCL-1 overexpressing tumors." (PMID 35443750, 2022). "However, human cancer cells containing amplifications of the Mcl-1 anti-apoptotic gene upregulate the Mcl-1 protein level for its survival and growth." (PMID 35457012, 2022). "In addition, Mcl-1, as the pro-survival Bcl-2 family member, inhibits apoptosis by blocking cell death in numerous cancers." (PMID 36457505, 2022). "Whilst detail of the specificity and direct pro-apoptotic impact of some of these drugs is currently unknown, preclinical evidence strongly indicates that MCL-1 can be effectively inhibited to confer an anti-cancer effect in vitro and in vivo." (PMID 35349392, 2022). "Given that these apoptosis-related proteins including Mcl-1 are involved in drug sensitivity of cancer cells, the balance of the apoptotic signal might be one of the important factors to determine the response to ASP1235 monotherapy." (PMID 36537913, 2022). "Targeting Mcl-1 by a small molecule enhances RS sensitivity to cancer therapy." (PMID 35875060, 2022). "Moreover, several studies have demonstrated that downregulating Mcl-1 expression or reducing its stability benefits the treatment of a variety of cancers." (PMID 35301297, 2022). "In addition to anti-apoptosis, MCL-1 also promotes epithelial-mesenchymal transition of human cancer cells." (PMID 35221802, 2022). "Targeting MCL-1 enhances DNA replication stress sensitivity to cancer therapy." (PMID 34384473, 2021). "Therefore, the combination of Dox and Mcl-1 siRNA served as a powerful antitumor regime as it targeted multiple vital pathways for cancer and thus warrants further assessment including in vivo experiments." (PMID 33919902, 2021). "The antiangiogenic properties through inhibition of VEGFR and PDGFR in endothelial cells are thought to be the key to its efficacy, but sorafenib has also been shown to demonstrate apoptotic effects on cancer cell lines through regulation of MCL-1 and the BCL-2 family of proteins." (PMID 34829820, 2021). "Moreover, imperatorin can augment the cytotoxicity of gamma-delta T cells against CD133-positive cancer via targeting myeloid cell leukemia 1 (MCL1), an endogenous apoptosis inhibitor." (PMID 34575983, 2021). "Thus, there has been considerable interest in targeting MCL1 in cancers reliant on MCL1 overexpression." (PMID 33824312, 2021). "While a large portion of these studies, especially those since 2017, are characterizing MCL1-specific BH3 mimetics in various cancer cell types, it is clear that MCL1 plays a larger, understudied role in many aspects of cellular maintenance and stress response." (PMID 34475520, 2021). "Although more extensive tolerability data are still pending, this assumption is also supported by several successfully completed phase I/II clinical trials in various types of cancers with AT-101, a small molecule simultaneously targeting MCL1, BCL2 and BCL-xL." (PMID 34564697, 2021).
cancer (continued). "Some biological functions of some nodes in this network are well known to be relevant for cancer progression as PTEN which is a tumor suppressor altered in some types of cancer, as well as others like MCL1 which is an anti-apoptotic protein altered in some types of cancers." (PMID 33649335, 2021). "To further confirm whether Mcl-1 level affects RBE, we reanalyzed proton RBE37 values used for our previous report and took normalized expression data of Mcl-1 from a previous quantitative proteomics study of 375 cancer cell lines." (PMID 33806487, 2021). "In various cancers, TYK2 overexpression or GOF mutations lead to STAT1 or STAT3 activation and upregulation of anti-apoptotic proteins, including B-cell CLL/lymphoma-2 (BCL-2) and myeloid cell leukaemia-1 (MCL-1)." (PMID 34439323, 2021). "The MCL-1 locus is commonly amplified across various cancer types in humans." (PMID 34336857, 2021). "Here, we present the pathological and treatment role of MCL-1 in different kinds of cancers." (PMID 33883020, 2021). "Moreover, genetic mouse cancer models have also demonstrated that Mcl-1 is essential for the survival of multiple tumor types." (PMID 34336857, 2021). "In addition to ABT-199 and ABT-263, other Bcl-2 family inhibitors have been evaluated in clinical trials for cancer treatment, including molecules targeting MCL-1 (A-1210477, S63845, AMG 176, AZD5991)." (PMID 33494434, 2021). "This induced cancer cell death following cytokinesis failure results from the intrinsic caspases 3 and 9-mediated apoptotic pathway and is more efficient in cancer cell lines harbouring low level of the anti-apoptotic Bcl-2 and Mcl-1 proteins." (PMID 34294140, 2021). "Our results demonstrated that the median mRNA expression of anti-apoptotic members (Bcl-2, Mcl-1, Bcl-xL) was lower in cancer than normal tissues, while the expression of pro-apoptotic members (Bid, Bim, Bax, Bak) prevailed in cancer tissues, compared to normal tissues." (PMID 35008345, 2021). "Therefore, our results suggest that the inhibition of BMI-1 induces DUB3-dependent Mcl-1 degradation, resulting in the enhancement of cancer apoptosis." (PMID 34576269, 2021). "Importantly, the Mcl-1 locus was shown to be recurrently amplified across multiple tumor types (∼10%) in a large-scale cancer genome study, and Mcl-1 was found to be highly expressed across a panel of 729 human cancer cell lines." (PMID 34336857, 2021). "For these reasons, a significant increase of Mcl-1 may contribute to apoptotic escape and promote cancer cell survival via oncogenic signaling pathways." (PMID 33919902, 2021). "Moreover, STAT3 signaling pathway positively regulates CyclinD1, Survivin, Bcl-2, Bcl-XL, and Mcl-1 to facilitate cancer cell cycle progression." (PMID 34179090, 2021). "Moreover, the existence of BAK/MCL1 complexes predicted sensitivities of cancer cells to the recently developed MCL1 inhibitor S63845 and the conventional chemotherapy drug paclitaxel." (PMID 34385422, 2021). "This implies that MCL1 can be a therapeutic target to improve the efficacy of cancer treatment." (PMID 34156978, 2021). "This suggests that, while MCL1 inhibitors may be beneficial for some cancer cell types that rely on the BH3-binding pocket, resistant CSCs like those described here would be spared." (PMID 34475520, 2021). "Moreover, MCL-1 is frequently amplified or overexpressed in a broad spectrum of cancers to promote tumor cell survival, suggesting its oncogenic role." (PMID 33471866, 2021). "Subsequently, the inhibition of MCL-1 was required to sensitize cancer cells to navitoclax." (PMID 34575429, 2021). "Collectively, MCL1 elicits pro-survival functions outside of its canonical regulation as a Bcl-2 family member, as it increases calcium oscillations from the ER and induces mitochondrial calcium uptake, which ultimately promotes cancer cell migration." (PMID 34475520, 2021).
cancer (continued). "Indeed, we identified with DBP anti-apoptotic changes in the BCL-2 family after treatment, particularly involving MCL-1 – a pro-survival strategy previously observed in adult cancers." (PMID 34568318, 2021). "In addition to confirming the reduction of MCL-1 level by KRIBB11 in other types of cancer cells, such as A172 cells, our present study revealed that the decrease in MCL-1 expression is responsible for the KRIBB11-mediated apoptosis of A172 cells." (PMID 34299435, 2021). "In addition, the increase of MCL-1 protein in cancer cells after treatment with S63845 has been demonstrated by other authors." (PMID 33921161, 2021). "Taken together, our data suggest that BCL-XL and MCL-1 could contribute complementarily to maintaining cancer cell survival and co-inhibition, therefore dramatically enhances cytotoxicity." (PMID 33917026, 2021). "The ability of DMC and OSU to downregulate the expression of these anti-apoptotic proteins (e.g., Mcl-1, Bcl-2) may therefore represent an appealing strategy to re-sensitize cancer cells to chemotherapeutic agents." (PMID 34356673, 2021). "Thus, MCL-1 is a potential therapeutic target for restoring cell apoptosis in multidrug-resistant cancers." (PMID 33883020, 2021). "Thus, understanding the role of MCL1 across diverse cancer cell types and endogenous tissues is critical as MCL1 inhibitors progress through clinical trials." (PMID 34475520, 2021). "Over recent years, Mcl-1 has attracted attention as a potential therapeutic target in cancer." (PMID 33627786, 2021). "Dinaciclib has been used as an MCL-1 inhibitor in several cancer paradigms." (PMID 33589591, 2021). "Bax is retrotranslocated from the mitochondria by Bcl2, Bcl-xl, and Mcl1 in resting cancer cells." (PMID 33589622, 2021). "Thus, targeting Mcl-1 has been considered as a promising approach for cancer treatment since its overexpression has been widely reported in both hematological and solid tumors." (PMID 34066632, 2021). "Therefore, reducing Mcl-1 expression, by direct or indirect inhibition, can sensitise resistant cancer cells to BH3 mimetics." (PMID 33627786, 2021). "This might suggest that inhibition of apoptosis via inducing Mcl-1 expression protects cancer cells from stress in Stat1-overexpressing cells." (PMID 34685622, 2021). "Gene expression analysis across many cancers also showed Mcl1 is amplified in ∼10% of cases." (PMID 34515749, 2021). "Furthermore, the expression of IAP family members, such as c-IAP1, c-IAP2, survivin, XIAP and livin, and Bcl-2 family members, such as Bcl-2, Mcl-1, Bak, and Bad, which play critical roles in cancer cells apoptosis regulation, was examined by western blotting." (PMID 34926237, 2021). "However, the most promising potential therapeutics in pre-clinical models appear to be the Mcl1 inhibitors, particularly when administered in combination with Venetoclax, Navitoclax, death inducing ligands and conventional anti-cancer drugs." (PMID 34753495, 2021). "Since BCL-2 and MCL-1 proteins may have overlapping anti-apoptotic functions with BCL-XL in cancer cells, we compared the impact of their mRNA expression levels, either alone or in combination with CDK1, CDK6 and WEE1, on the overall survival of TNBC patients." (PMID 34646365, 2021). "HSF1 inhibition by using HSF1 shRNAs or KRIBB11 decreased the expression of HSF1 downstream proteins, such as HSP70 and HSP27, and also decreased the expression of HSP90/HSP70/BAG3 client proteins, such as BCL2, MCL1, EGFR, MET, and AXL, causing apoptosis of EGFR-TKI-resistant cancer cells." (PMID 34203709, 2021).
cancer (continued). "Thus, by inhibiting the expression of PTEN, miR-21 upregulates the expression of the anti-apoptotic proteins MCL-1 and/or Survivin, and consequently promotes cancer cell survival." (PMID 34066762, 2021). "Besides, constitutively activated STAT3 can also upregulate the expression of anti‐apoptotic genes, including BCL-XL and MCL-1, in human cancer cells." (PMID 34354046, 2021). "MCL1 is one of the most highly amplified genes in a variety of cancers." (PMID 34156978, 2021). "Over the last few years, this protein has received particular attention as a target for cancer therapy due to the fact that it is often overexpressed in cancer cells and that the MCL1 locus is one of the most frequently amplified regions of the human genome across a wide variety of cancers." (PMID 34028599, 2021). "Because the small-molecule inhibitors targeting ANO1 have been to date evaluated only in vitro, we investigated whether MCL1-mediated decrease of cancer cell viability is achievable by utilization of MCL1 inhibitor that is under clinical investigation." (PMID 33803266, 2021). "Ultimately, this could provide a novel area for combination therapy with MCL1 inhibition and DNA-damaging agents as a novel therapeutic strategy in cancer." (PMID 34475520, 2021). "MCL1 deletion has been shown to drastically affect several cell types including the colonic epithelium, however specific MCL1 inhibitors seem to be well tolerated in several preclinical cancer models." (PMID 34117376, 2021). "It is plausible to speculate that many of the malignancies with elevated expression of Mcl-1 will benefit from treatment with Mcl-1 specific inhibitors either alone or in combination with other anti-cancer agents." (PMID 34336857, 2021). "Multiple roles of MCL1 have been reported in normal cellular development and cancers." (PMID 34638252, 2021). "Increased expression of MCL‐1 is a mediator of resistance to venetoclax in cancer." (PMID 33347715, 2021). "Therefore, CDK9 inhibition reduces messenger RNA (mRNA) transcription and prevents the expression of target genes (e.g. Myc and Mcl-1), which together regulate proliferation and cancer cells survival." (PMID 33632038, 2021). "Other Usp9x substrates in cancer (e.g., Ets-1, MCL-1) may also contribute to the anti-tumor activity of Usp9x inhibition and warrants further assessment." (PMID 33613844, 2021). "The combination therapies could trigger both Mcl-1 dependent and independent pathways, which might advocate the potential utility for cancer therapy." (PMID 33919902, 2021). "Since BCL-2 family members and MYC act cooperatively in cancers, inhibiting MCL-1 could be a potential approach for MYC-involved cancers." (PMID 34372899, 2021). "Mcl-1 is one of the key targets in contemporary anti-cancer research along with Bcl-2 and Bcl-xL13." (PMID 33257694, 2020). "MCL1, an anti-apoptotic protein that controls chemosensitivity and cell fate through its regulation of intrinsic apoptosis, has been identified as a high-impact target in anti-cancer therapeutic development." (PMID 33144577, 2020). "Moreover, the unbalanced anti- and pro-apoptotic isoform expression results from alternative splicing of key apoptotic factors, such as Bcl-x, Bcl-2L11, and myeloid cell leukemia-1 (Mcl-1), possibly promoting cancer initiation and/or maintenance." (PMID 33052877, 2020). "Rationale: MCL-1 is up-regulated in cancer and a target for cancer treatment." (PMID 32802178, 2020). "MCL1 is one of the most frequently amplified genes in cancer." (PMID 32645016, 2020). "However, BCL-XL/MCL-1-mediated “dual apoptosis protection” also impairs response of cancer cells to chemotherapy." (PMID 32312973, 2020). "Drug-resistant cancer cells in these hematologic neoplasms are induced by overexpression of the antiapoptotic B-cell lymphoma 2 (Bcl-2) protein families, such as Bcl-XL, Bcl-2, and Mcl-1." (PMID 33312200, 2020). "In line with previous data, MCL-1 was significantly gained and highly expressed in 22 cancer types." (PMID 32913197, 2020).